CCL20 (C-C motif chemokine ligand 20)
Diseases named in the same sentence as CCL20 in open-access papers (continued):
Sharing a sentence is not in itself a finding about the gene and the disease.
tumor (continued). "We further examined CCL20 expression in tumor tissue derived from mice treated with DT, we found that selective depletion of macrophages resulted into a marked decrease in both CCL20 mRNA level and CCL20 protein level in tumor mass compared with DTmu treatment." (PMID 21559338, 2011). "We sought to characterize the role of the CCL20/CCR6/IL-17 axis in NSCLC tumor growth." (PMID 21949768, 2011). "To investigate whether TAMs promote the release of CCL20 from CMT93 tumor cells in vivo, we grafted GFP+ CMT93 tumor cells in CD11b-DTR transgenic mice." (PMID 21559338, 2011). "Take together, this data suggest that CCL20/CCR6 interactions in the tumor microenvironment may stimulate NSCLC disease progression." (PMID 21949768, 2011). "On the other hand, there is a growing body of evidence supporting the hypothesis that CCL20 production by cancer cells promotes tumor growth and invasiveness." (PMID 19340288, 2009). "The majority of tumor samples that expressed CCL20 co-expressed CCR6." (PMID 19340288, 2009). "Whereas the ligand for CCR6, CCL20, was expressed in 34 out of 52 tumor samples (65.4%)." (PMID 19340288, 2009). "Moreover, antibodies to CCL20 inhibited the invasion of tumor cells into surrounding tissues similarly to the skin and muscle (data not shown)." (PMID 19340288, 2009). "Furthermore, overexpression of CCL20 in tumor cells promotes growth and adhesion in vitro and increased tumor growth and invasiveness in vivo." (PMID 19340288, 2009). "Here we show that CXCR4 up-regulates the expression of the chemokine CCL20 in various cancer cells, and that CCL20 in turn promotes in an autocrine manner the survival, proliferation and adhesion of cancer cells in vitro and enhances xenograft tumor growth, vascularization and invasion in vivo." (PMID 19340288, 2009). "A significant decrease in tumor growth was observed in anti-CCL20-treated mice." (PMID 19340288, 2009). "Recent studies using antigens coupled to antibodies directed against the mouse DC antigen DEC-205 or attraction of DC to the tumour via retrovirus-mediated expression of the DC-attracting chemokine CCL20 illustrate the possibility to directly load tumour antigens onto DC in vivo." (PMID 16953240, 2006). "Additionally, CXCL17 influences the tumor milieu by upregulating CCL20 expression in HGC27 cells." (PMID 41459506, 2025). "Further analysis of the six core LRPS genes showed that CCL20 was also significantly positively correlated with Treg, M0 macrophage, and neutrophil infiltration, suggesting a role for CCL20 in modulating immunosuppressive cell infiltration and tumor progression." (PMID 40741410, 2025). "In addition, the expression of several pro-inflammatory cytokines and chemokines such as IL-1β, IL-22, TNF-α, CXCL1, CXCL2, CCL17 and CCL20 were reduced in IL-38KO mice, suggesting that IL-38 promotes tumour growth and development in cSSC through promoting an inflammatory tumour environment." (PMID 40057603, 2025). "However, in Balb/C mice, CXCL3 demonstrated a stronger tumor inhibitory effect than did CCL20." (PMID 40179015, 2025). "However, the use of NOD‐SCID mice in the xenograft model limits our ability to assess whether CCL20 inhibition affects other immune cell populations within the tumour microenvironment." (PMID 40913253, 2025). "Since our previous studies have demonstrated and characterized that irradiated tumor cell–derived microparticles (RT-MPs) exhibit potent tumoricidal and immunostimulatory properties, we wondered whether RT-MPs mediate CCL20 secretion by macrophages, thereby promoting γδ T cell infiltration." (PMID 41055972, 2025). "However, the impact of CCL20 on the tumor immune microenvironment is weaker than that of CXCL3." (PMID 40179015, 2025). "Furthermore, it has been proposed that high levels of IL-22, IL-10, and CCL20 may determine, as a cascade event, the overexpression of IL-22–STAT3–CCL20–CCR6 thought to be associated with a tumor’s ability to spread to the lymph nodes and internal organs." (PMID 38607023, 2024).
tumor (continued). "In addition, increased CCL20 could further activate NF-κB signaling and thus form a feedforward loop to drive tumor progression in multiple cancers, which needs further validation in CRC." (PMID 38228802, 2024). "Moreover, Th17 cells have been shown to induce robust activation of CD8+ T cells and could also stimulate the production of the chemokine CCL20 by tumor tissues, promoting the infiltration of DC in a CCL20-CCR6 dependent manner." (PMID 39093451, 2024). "Thus, the immune chemokines CXCL8, CXCL3, and CCL20, which are positively associated with SLC7A11, have SLC7A11-like functions in the development of tumours and provide evidence of association at the tumour immune microenvironment level for poor prognosis in ACC patients with SLC7A11high." (PMID 37919768, 2023). "Similarly, in the MC38 hot tumor mouse model, CCL20 and IL-1β also drove ILC3s infiltration and lymphocytes recruitment to inhibit tumor growth and also enhanced the reactivity to ICB including anti-PD-1 and anti-CTLA-4, significantly extending the survival rate." (PMID 37122757, 2023). "In addition, we detected CCL20 mRNA values in both normal and tumor cell lines." (PMID 36814485, 2023). "Furthermore, migration of IL-10-secreting regulatory CD4+ T cells (Tregs) into the tumor environment can be induced by EBNA1-mediated upregulation of CCL20 on tumor cells, leading to the induction of immune tolerance through the suppression of cytotoxic CD8+ T cells." (PMID 37033971, 2023). "However, sometimes CCL20 can promote anti-tumor immunity via the reconstruction of TIME." (PMID 35864953, 2022). "Given the CCL20/CCR6 axis plays a critical role in inflammatory diseases 32, we speculate that high CCL20 expression may be associated with the locally active inflammatory state of the tumor, which enhances the pyroptosis marker expression." (PMID 35864953, 2022). "Therefore, CCL20 and Th17 may play a dual role in tumor immunity and provide a deeper understanding of the role of CCL20 and Th17 in the immune response." (PMID 36119033, 2022). "It has also been shown that injection of recombinant murine CCL20 protein into the tumor site promotes tumor progression and increases Treg recruitment, suggesting that the concentration of CCL20 should be considered as a prognostic factor for tumor dissemination." (PMID 35408440, 2022). "It was reported that CCL20 in a tumor could recruit Th17 in TIME." (PMID 35459193, 2022). "Similarly, one study revealed that CCL20 could recruit dendritic cells and that is induced anti-tumor immunity against GC." (PMID 36614059, 2022). "However, within the tumor microenvironment, such levels of CCL20 expression may be biologically significant as an autocrine factor and/or modulator of infiltrating immune cells." (PMID 34725321, 2021). "Therefore, we hypothesized that CCL20 might have a biological effect on neutrophils infiltrated into the tumor microenvironment." (PMID 34519637, 2021). "Similarly, increased expression of microRNA21, induced by HPV16 E6 and E7, may lead to decreased CCL20 expression and tumor progression and carcinogenesis." (PMID 33888832, 2021). "Further studies are necessary to elucidate the role of these signaling pathways in vivo as the tumor microenvironment may be involved in the production and/or the effects of CCL20, HGF and MSP through cells such as macrophages, cancer-associated fibroblasts, and myofibroblasts." (PMID 34853656, 2021). "Furthermore, tumor hyperthermia potentiated immune system responses through release of exosomes containing chemokines (CCL2, CCL3, CCL4, CCL5, and CCL20), HSPs, and tumor antigens to the antigen-presenting cells and facilitated tumor cell attack and tumor cell surface modulation." (PMID 34337063, 2021). "Furthermore, we found that vessels in the vicinity of CCL20-positive tumour tissues expressed CCR6." (PMID 32601464, 2020). "Next, we investigated whether CCL20 influences tumour vascularisation." (PMID 32601464, 2020).
tumor (continued). "Moreover, we show that CCL20 stimulates angiogenesis, which fosters tumour growth and progression." (PMID 32601464, 2020). "We hypothesised that tumour-derived CCL20 creates a microenvironment that enhances tumour growth." (PMID 32601464, 2020). "Furthermore, CCL20 blockade suppressed tumor progression and restored 5-FU sensitivity in CRC." (PMID 31395078, 2019). "In addition, we have shown that EBV-dUTPase up-regulates the expression of CCL20 (335-fold), which, in turn, may increase migration and trafficking of regulatory T cells (Tregs) into the tumor environment." (PMID 29723986, 2018). "Thus, u50535 can promote tumor cell proliferation and migration by regulating CCL20 expression." (PMID 29970882, 2018). "In addition, SKCXCR2-derived tumor tissues maintained high CCL20 mRNA expression and induced greater CCL24 and CXCR4 compared to SKCXCR2 cells, indicating the shift of chemokine network during the peritoneal spreading of tumor cells via interaction with other cell types in tumor microenvironment." (PMID 27723802, 2016). "CCL20 can be also produced by Th17, which could self-consolidate their adhesion to the tumor site." (PMID 27589729, 2016). "Our findings suggest that the presence of CCL20 in the tumor may indicate a poor prognosis of HCC." (PMID 26300991, 2015). "However, in non-tumor region, CCL20 is secreted mainly by Kuffer cells (middle)." (PMID 21935436, 2011). "Strikingly, in the co-culture of CMT93 and mouse peritoneal macrophages, CMT93 cancer cells produced 26.4-fold more CCL20 than macrophages at mRNA levels, suggesting that macrophages may interplay with cancer cells for production of CCL20 in the tumor microenvironment." (PMID 21559338, 2011). "This may suggest that autocrine secretion of CCL20 may drive tumor growth." (PMID 19340288, 2009). "Enhanced expression of the CCL20 chemokine, the ligand of CCR6, was observed in cancer tissue compared to the normal condition, along with an increased CCL20 gradient in mouse tumor-draining LNs." (PMID 42093985, 2026). "Accumulating evidence indicates that inflammatory mediators-including CCL2, CCL3, CCL5, CXCL1, CCL20, TNF-α, IL-6, IL-8, and TGF-β-contribute to tumor growth, metastasis, immune modulation, and therapeutic resistance." (PMID 42245673, 2026). "Flow cytometric analysis of tumor tissue revealed that both the CXCL10 OE and CCL20 OE groups had a large number of immune cell infiltrates, while the empty vector-transfected 5-8F group lacked the ability to induce immune cell infiltration." (PMID 41399390, 2026). "In this study, high-throughput sequencing was employed to analyze cytokines secreted by NPC tumor cells, revealing CXCL10, which promotes immune responses, and CCL20, which mediates immune suppression." (PMID 41399390, 2026). "Tumor cells, along with other stromal and immune cells in the TME, secrete chemokines including CCL22, CCL20, and CXCL12, which bind to CCR4, CCR6, and CXCR4 on Tregs and direct their recruitment and activation within the TME." (PMID 41890756, 2026). "This review compiles current knowledge on the significance of lesser-known chemokines in MM tumor processes, including CXCL13, CCR2 ligands (CCL2 [MCP-1], CCL7 [MCP-3]), CCL4, CCL5 (RANTES), CCL17, CCL20, CCL27, CCL28, and CX3CL1 (fractalkine)." (PMID 41749925, 2026). "Compared to adjacent normal cells, tumor colonocytes overexpressed chemokines (CXCL1, CXCL2, CXCL3, and CCL20), showing significant effects on inflammatory processes and immune cell recruitment." (PMID 40240912, 2025). "This suppression of CCL20 reduces activation of the CCL20-mediated JAK-STAT signaling pathway, thereby inhibiting tumor progression." (PMID 40444282, 2025). "Specifically, the infiltration of TREM-1 + TAMs in HCC were shown to mediate hypoxia-induced tumor immunosuppression and resistance to anti-PD-L1 therapy, by recruiting CCR6 + Foxp3 + Treg cells via the CCL20/ERK/NF-κB pathway." (PMID 40380196, 2025).
tumor (continued). "CCL20, a ligand for CCR6, draws CCR6-expressing Tregs to the TME, driving tumor growth and worsening patient prognosis." (PMID 41445742, 2025). "We compared the effects of CXCL3 and CCL20 on tumor progression and found that knocking down either CXCL3 or CCL20 substantially inhibited tumor progression in both Balb/C mice and nude mice." (PMID 40179015, 2025). "Radiation-induced microparticles containing double-stranded tumor DNA led to activation of the cGAS/STING pathway in macrophages, promoting γδ T cell recruitment through CCL20 signaling." (PMID 41392975, 2025). "CCL20 was consistently upregulated in both OSCC tissues and saliva, particularly in advanced stages, implying a role in tumor progression." (PMID 40869423, 2025). "For instance, human tumor microenvironments exhibit elevated expression of CXCL12 (CXCR4 ligand) and CCL20 (CCR6 ligand), creating a chemokine gradient that potentiates Th17 cell infiltration into tumors." (PMID 41296387, 2025). "Emerging evidence has shown that CCL20 and its receptor CCR6 are important players in endothelial cell-mediated tumor progression." (PMID 39985603, 2025). "Macrophage inflammatory protein (MIP-3α), also known as the chemokine CCL20, has the ability to infiltrate various types of immune cells in the tumor microenvironment, including dendritic cells (DCs), regulatory T lymphocytes (Tregs), and Th17 helper cells." (PMID 40636107, 2025). "Breast cancer and stromal cells in TME cells secrete chemokines CCL2, CCL5 (RANTES), CCL20, CCL22, and CXCL12 which, by binding to the corresponding receptors, induce Treg homing to tumor tissue." (PMID 40940764, 2025). "High expression of CCL20 not only promotes the appearance of EMT in HCC cells, but also activates STAT3 to induce Th9 helper T cells with tumor‐promoting effects targeting the HCC tumor microenvironment." (PMID 40145607, 2025). "Jingyao Lian reported that CCL20 binds to its receptor CCR6, facilitating the aggregation of Tregs in the ESCC TME and accelerating tumor proliferation." (PMID 40134607, 2025). "To explore the immune response of CCL20 and CXCL3, we constructed stable knockdown of Ccl20 and Cxcl3 in orthotopic implanted tumor mouse models." (PMID 40179015, 2025). "Chemokines and cytokines such as CSF2, CCL12, CCL20, IL1B, and CXCL3/5/6 are significantly upregulated in the tumor microenvironment, indicating that the body is extensively recruiting and activating myeloid immune cells." (PMID 41415031, 2025). "CCL20, via the CCL20/CCR6 axis, has been documented to promote tumor progression in numerous different types of cancer, including breast, hepatocellular, colorectal, and lung." (PMID 40114916, 2025). "HCC‐mediated CCL20 production has been shown to recruit CCR6+CD5+ B cells, promoting angiogenesis and thus facilitating tumour growth." (PMID 40913253, 2025). "These cells are capable of migrating to CCL20-expressing tumor tissues, including CRC, and exhibit enhanced IFN-γ production, thereby improving the tumor microenvironment." (PMID 40771692, 2025). "Concomitantly, expression of established M2 markers CCL20 and MMP9 increased during this differentiation, confirming the predominant M2 phenotype of tumor-infiltrating macrophages." (PMID 41346635, 2025). "Tumor cell-derived dsDNA-containing microparticles activate macrophage cGAS-STING pathway, inducing CCL20 to recruit IL-17-producing γδ T cells, driving radioresistance." (PMID 41055972, 2025). "Irradiated tumor cells release dsDNA-containing microparticles, which activate the cGAS-STING/NF-κB pathway in macrophages and upregulate chemokine CCL20 to recruit γδ T cells." (PMID 41055972, 2025). "In syngeneic tumor-bearing mice, CCL20/CCR6 distortion rejuvenated T cell activity and prolonged the survival of tumor-bearing mice." (PMID 39985603, 2025).
tumor (continued). "Specifically, patients with tumours exhibiting high expression of ECM‐related (SPP1 and MUC5B) and complete active related genes (CFB and CCL20) in either the epithelial or macrophage compartment had significantly shorter disease‐free survival (DFS)." (PMID 40847563, 2025). "Network analysis highlighted immune-related hub genes (CXCL1, CCL20, IL12B, and STAT4) involved in chemotaxis, leukocyte migration, and cytokine signaling, linking immune dysregulation to tumor development." (PMID 40445003, 2025). "The cluster 6 monocytes were defined by high expression of multiple pro-tumor genes (IL1B, SERPINB2, CCL2, CXCL1, CXCL5, CXCL8, CCL3, CCL20)." (PMID 40176808, 2025). "The results demonstrated that inhibiting the activation of this pathway effectively diminished CCL20 secretion in TAMs and hindered the recruitment of CCR6+ Tregs, consequently reducing the proportion of Tregs and impeding tumor growth." (PMID 39853961, 2025). "They preferentially home to tumours through chemokines such as CCL2 and CCL20, making them advantageous for solid tumour targeting." (PMID 41292193, 2025). "Key chemokine receptors, such as CCR2, CCR6, CCL20 and CXCR4, have been identified as pivotal contributors to Treg recruitment at tumor sites." (PMID 41445742, 2025). "In a xenograft tumour mouse model, tumour growth and monocyte infiltration were inhibited in GLI1 or CCL20 knockout PLC5 cells." (PMID 40913253, 2025). "The NOD‐SCID mice were transplanted with wild‐type (WT) PLC5 cells, GLI1 KO or CCL20 KO PLC5 cells, and the tumour growth was monitored over time." (PMID 40913253, 2025). "Mechanistically, it was demonstrated that radiotherapy triggers the release of dsDNA-containing RT-MPs from tumor cells, which activate the cGAS-STING/NF-κB signaling pathway in macrophages, leading to the upregulation of CCL20 expression." (PMID 41055972, 2025). "CCL20 facilitates tumor invasion and MMP-2/9 secretion in basal-like TNBC, with high CCL20 expression predicting reduced metastasis-free and overall survival." (PMID 40909271, 2025). "By analyzing the bioinformatics database and verifying the cancerous and non-cancerous tissues of different patients, we found a significant upregulation of CXCL13 and CCL20 in NSCLC versus normal lung tissue, establishing a tumor-directed chemokine gradient." (PMID 40764989, 2025). "We demonstrated that Gal1‐induced TAMs activated the CCL20 release via stimulating the PI3K/AKT/NF‐κB pathway, therefore triggering the recruitment of CCR6+Foxp3+ Tregs that impaired the anti‐tumor response of CD8+ T cells." (PMID 39853961, 2025). "Overexpression of CCL20 in HCC cells markedly enhanced proliferation and invasion, consistent with previous reports of CCL20’s involvement in tumor cell migration and invasiveness." (PMID 40741410, 2025). "As a chemokine, CCL20 modulates the TME by recruiting immune cells, potentially fostering tumor cell proliferation and invasion to accelerate HCC progression." (PMID 40741410, 2025). "Studies have shown that CAFs upregulate levels of C-C motif chemokine ligands such as CCL2, CCL5, and CCL20 to coordinate activation of HCC cell ERK/PKM2 and TGF-β pathways to enhance tumor metastasis phenotype and regulate tumor metabolism." (PMID 40028341, 2025). "In vitro migration assays further demonstrate that CCL17, CCL20, and CCL22 exert chemotactic effects on tumor-derived Th17 cells." (PMID 40134607, 2025). "The CCL20/CXCL5 axis plays a crucial role in the interaction between TAMs and ATCSCs, establishing a progressive tumor microenvironment." (PMID 40091357, 2025). "IGF-1 and CCL20 promote tumour progression, while SIRPα interacts with CD47 expressed on tumour cells to inhibit microglial phagocytosis." (PMID 39364322, 2024). "Our findings unveiled a significant upregulation in a variety of cytokines in UPP1-overexpressing tumor cells, including TGF-β1, GM-CSF, IL-1β, IL-6, IGFBP-3, CXCL5, CCL20, and VEGF, with TGF-β1 being the most prominently elevated." (PMID 38331898, 2024).